SMAD4 (SMAD family member 4)
Diseases named in the same sentence as SMAD4 in open-access papers (continued):
Sharing a sentence is not in itself a finding about the gene and the disease.
colorectal cancer (continued). "Prior studies have shown that loss of SMAD4 is associated with worse recurrence-free and overall survival in patients with stage III colorectal cancer." (PMID 35892903, 2022). "Using a discovery dataset of 250 colorectal cancer patients, we analyzed expression of BMP/Wnt target genes for association with SMAD4 expression." (PMID 34114372, 2022). "This research helps to enlighten the role of the SMAD4–201 transcript in colorectal cancer and its translational potential as a predictive and prognostic biomarker." (PMID 35034624, 2022). "First recognized as a poor prognostic factor in colorectal cancer, more recent studies have identified a correlation between SMAD4 expression and 5-FU sensitivity." (PMID 35685436, 2022). "Next, chromosome 18q21 is often deleted with the tumor suppressor genes SMAD2, SMAD4 and deleted in colorectal carcinoma (DCC)." (PMID 36611932, 2022). "Consistently, low level of SMAD4 has been found to associate with high MMP-9, resulting colorectal cancer malignance." (PMID 34743754, 2021). "Smad4 has been evaluated for its tumor suppressive role in colorectal cancer, colon cancer and its tumor-progressive role in hepatocellular carcinoma." (PMID 34742256, 2021). "In colorectal cancer, SMAD4 has also been previously shown to accumulate in the nucleus in the EMT process and is associated with lymphatic invasion." (PMID 33746597, 2021). "SMAD4 has been extensively studied and found to have a role in the tumorigenesis of many human cancers including gastric and colorectal cancers." (PMID 34012911, 2021). "Patients with mesenchymal subtype colorectal cancer have a poor prognosis, in particular, patients with stroma-rich tumors and aberrant SMAD4 expression." (PMID 33810241, 2021). "For example, in colorectal cancer, knockdown or deletion of Smad4 promoted cancer migration and invasion via activating AKT signaling." (PMID 33372356, 2021). "Meanwhile, DUSP4 can directly deubiquitinate and stabilize Smad4 protein, hence further promote proliferation and metastasis of colorectal cancer cells." (PMID 32897241, 2020). "Specifically, miR-144 was down-regulated in colorectal cancer cells and tissues, and suppressed cancer development by directly targeting SMAD4 and CXCL11." (PMID 32351538, 2020). "Accumulating loss of SMAD4 leads to up-regulation of CCL15 and CCR1 expression, followed by higher activity and expression of MMP-9, ultimately causing colorectal cancer malignance." (PMID 30979374, 2019).
colorectal cancer (continued). "Second, MG132 treatment, the inhibitor of proteasome, disrupted TRIM47-induced SMAD4 downregulation in colorectal cancer cells." (PMID 30979374, 2019). "The results showed that overexpression of SMAD4 significantly reduced colorectal cancer cell proliferation and invasion induced by TRIM47 in SW480 cells." (PMID 30979374, 2019). "In our study, the expressions of DCC, Smad2, Smad4, hMLH1, hMSH2, and hMSH3 proteins had been changed, which regulated the colorectal cancer pathway." (PMID 30792708, 2019). "(A) Representative images of SMAD4 protein expression in colorectal cancer tissues and paired adjacent tissues using IHC in Renji dataset (Cohort 2, n = 180)." (PMID 30979374, 2019). "SMAD4 protein expression was lower in colorectal cancer tissues than the adjacent tissues (P < 0.05)." (PMID 30979374, 2019). "We examined the SMAD4 protein expression by immunohistochemical staining assay in 180 paraffin-embeddded colorectal cancer and adjacent normal tissues (Cohort 2)." (PMID 30979374, 2019). "First, knockdown of TRIM47 increased the expression of SMAD4 in colorectal cancer cells and the data were verified in gain function assay as well." (PMID 30979374, 2019). "To understand the molecular mechanism by which TRIM47 promotes cell proliferation and invasion of colorectal cancer, we examined the protein expression of SMAD4." (PMID 30979374, 2019). "For example, TRIM47 overexpression promoted colorectal cancer cells proliferation and metastasis via ubiquitination and degradation of SMAD4." (PMID 31823782, 2019). "(B) Statistical analysis of SMAD4 protein expression in colorectal cancer tissues and paired adjacent tissues using IHC staining in Renji dataset (Cohort 2, n = 180, nonparametric Mann–Whitney test, P < 0.05)." (PMID 30979374, 2019). "The results revealed that SMAD4 expression was an independent predictor of colorectal cancer aggressiveness with significant hazard ratios for predicting clinical outcome." (PMID 30979374, 2019). "In sporadic colorectal cancers, the TGFBR2 and SMAD4 mutations are found in about 15% and 10% of patients, respectively." (PMID 29652830, 2018). "Among the MMR-proficient tumors, at least 8% had a germline in at least one gene (in some cases, mutations in high-penetrance colorectal cancer genes, such as APC, PMS2, MUTYH, SMAD4)." (PMID 29652830, 2018). "These proteins interacting with claudin-2 were often over expressed or activated in colorectal cancer (A ∩ E) but only Smad4 was the proteins that interacted with claudin-7 (A ∩ E)." (PMID 28698546, 2017). "Recently, our research group also reported that SMAD4 suppresses the development of malignant phenotypes of human colorectal cancer through interacting with HIF1α to suppress VEGF and MMP expression under hypoxic conditions." (PMID 24625091, 2014). "Recently, the miR-454 family has been reported to be up-regulated in human colorectal cancer tissues and cell lines by targeting Smad4." (PMID 24685242, 2014). "In colorectal cancer, patients with reduced SMAD4 expression frequently presented an unfavorable survival because of liver metastasis." (PMID 23158542, 2012).
colorectal cancer (continued). "As this lesion progresses to the late adenoma stage, there is loss of heterozygosity of the genes deleted in colorectal carcinoma (DCC) and SMAD family member 4 (SMAD4)." (PMID 24392268, 2012). "Juvenile polyposis syndrome, an inherited syndrome with high risk of colorectal cancer, is caused by germline mutation of BMPR1A or SMAD4, and importance of BMP signal is supported by its mouse model with transgenic Nog expression or with Bmpr1a inactivation." (PMID 22072987, 2011). "We report, that Smad4-reexpressing human colorectal cancer cells like adenoma cells respond to TNFα with a moderate increase of all three chains encoding laminin-332 and with synergistic induction in response to the combination of TGFβ and TNFα." (PMID 20307265, 2010). "Another gene, DCC (deleted in colorectal cancer), is found to be in close proximity to SMAD4 in the human 18q21.1-q21.2 region." (PMID 20707908, 2010). "Utilising a recently developed method of immunohistochemical staining for Smad4 protein, we focused on the specific impact of Smad4 protein expression on liver metastasis in colorectal cancer." (PMID 17088901, 2006). "Future research comparing early and advanced stages is required to investigate the tumour-suppressor pathway in colorectal cancer and to redefine the role Smad4 signalling plays in tumorigenesis." (PMID 12569386, 2003). "The aim of this study was to investigate the potential involvement of the Smad4 locus in early-stage colorectal cancers (stages I–III) in tumour samples from a randomised multicentre trial." (PMID 12569386, 2003). "We established that among the patients with colorectal cancer involved in this study, SMAD4 was deleted in 67% of cases." (PMID 12237773, 2002). "We observed that colorectal cancer patients with normal SMAD4 gene copy status had a three-fold higher benefit of 5FU-based therapy than those with SMAD4 deletion." (PMID 12237773, 2002). "Notably, UrCAs tend to exhibit a lower frequency of TERT and RB1 alterations than BAC, whereas SMAD4 and GNAS mutations, which are frequently observed in colorectal cancer, are more commonly identified in UrCA." (PMID 39857670, 2025). "Additionally, we observed that the low-expression group exhibited a high mutational load, with FBXW7, SOX9, AMER1, SMAD4, ARID1A, and B2M being the most frequently mutated genes in colorectal cancer." (PMID 40170839, 2025). "Despite the correlation established for Spp1 and Pak3 in mouse adenoma organoids, these two genes did not appear significantly differentially expressed in human colorectal cancer with respect to SMAD4 variants." (PMID 40348815, 2025). "SMAD4 deletion promotes colorectal cancer (CRC) expression of C-C Motif Chemokine Ligand 15 (CCL15) and recruits the CCR1 TAN (CCL15-CCR1 axis) with arginase-1 (ARG-1) and matrix metalloproteinase 9 (MMP-9) activities, thereby forming a pre-metastatic niche for disseminated tumor cells (e." (PMID 40160822, 2025). "Of the 76 Smad4 and TGF-β1 dependent genes identified in Apcfl/flSmad4fl/fl adenoma organoids, only 7 human equivalent genes were differentially expressed in SMAD4 mutated colorectal cancer (TCGA cohorts), including ID1low." (PMID 40348815, 2025).
colorectal cancer (continued). "Heterozygous or homozygous deletion of SMAD4 was first discovered in pancreatic ductal adenocarcinoma and later detected in various types of cancers, such as colorectal cancer, cholangiocarcinoma, gastric cancer, and prostate cancer, although with lower frequencies to some extent." (PMID 40224178, 2025). "In addition, CRC patients with SMAD4 mutations and high expression of DKK4 exhibit poor prognosis thereby demonstrating new therapeutic approaches for advanced colorectal cancers." (PMID 38461268, 2024). "Protein factors that could regulate transcription of SMAD4-213 via AnnoLnc2 predicted binding sites upstream of/overlapping TSS that are expressed in colorectal cancer are CDX2, CEBPB, ELF1, NCOA1, NCOR1, NCOR2 and TFAP4." (PMID 39132157, 2024). "The miR-20a-5p also suppressed the expression of SMAD4 in colorectal cancer cells." (PMID 38969714, 2024). "We aimed to explore this phenomenon at the cellular level on the example of a major tumor suppressor SMAD4 in search of molecular mechanisms in colorectal cancer that could be exploited for novel biomarkers or therapeutic approaches." (PMID 39132157, 2024). "In addition, our search of the UALCAN and TNMplot databases found that a lower level of SMAD4 gene expression correlates both with the development of colorectal cancer and with a higher cancer stage." (PMID 37237640, 2023). "Furthermore, genetic attenuation of YAP/TAZ activity alleviates dextran sulfate sodium (DSS)‐induced colitis and azoxymethane/dextran sulfate sodium (AOM/DSS)‐induced colorectal cancer in Smad4‐knockout mice." (PMID 37261975, 2023). "The Smad4 mRNA nano-lantern is also expected to have targeting capability as the RGD peptide it labeled with can target integrin αVβ3 which is highly expressed in colorectal cancer cells." (PMID 36894556, 2023). "Indeed, the relevance of EMT-TFs for the regulation of the EMT program over time has been recently reinforced by Frey and colleagues investigating the pro-metastatic phenotype of SMAD4-defective colorectal cancer cells." (PMID 38067168, 2023). "For instance, in hepatocellular carcinoma, lncRNA-MUF promotes EMT via the Wnt signaling pathway, and inhibits SMAD family member 4 (SMAD4) protein degradation in colorectal cancer cells, thereby activating the transforming growth factor beta (TGF-β) signaling pathway." (PMID 37542040, 2023). "Whilst a synthetic lethality interaction between BETi (OTX-015, i-BET151, JQ1) and SMAD4 expression has been reported in colorectal cancer cells, their potential association in OC has not been investigated thus far." (PMID 37060086, 2023). "As such, the level of SMAD4 mRNA in patients with advanced colorectal cancer could be used as a genetic marker of the response to adjuvant therapy with 5-FU." (PMID 37237640, 2023). "In colorectal cancer, the level of expression of the SMAD4 gene plays a role in inducing resistance to 5-FU-based therapy; however, the molecular mechanism underlying this phenomenon remains unknown." (PMID 37237640, 2023). "Furthermore, the same group showed that colorectal cancer cells with the loss of the tumor suppressor SMAD4 secreted CCL15 and recruited CCR1+ myeloid cells to assist tumor invasion in colorectal cancer patients." (PMID 35267547, 2022).
colorectal cancer (continued). "We showed, in this study, that SMAD4 mutation alone is not a sufficient biomarker for predicting prognosis in patients with colorectal cancer." (PMID 35892903, 2022). "Colorectal cancers are typified by alterations in several pathways, including adenomatous polyposis coli (APC) loss, the activation of the RAS/MAPK signaling pathway, and TGFβ (by SMAD4 inactivation) pathways." (PMID 34604084, 2021). "Additionally, a previous study deciphered that PGM5-AS1, which is downregulated in colorectal cancer, functioned as a molecular sponge to mediate SMAD4 expression by sponging miR-100-5p." (PMID 33407592, 2021). "In colorectal cancer, the mechanism of Smad4 regulation needs further study." (PMID 32897241, 2020). "SMAD4 is a tumour suppressor, and transcription factor of the TGF-ß pathway and loss of function alterations have been shown to cause, for instance, impaired response to chemotherapy in colorectal cancer." (PMID 32198650, 2020). "PPI network analysis demonstrated that SMARCD3 could physically interacted with MAPK14 (p38α), MYOD1 and SMAD4 etc., which indicated mechanistic insights underlying SMARCD3 related colorectal cancer metastasis." (PMID 33125346, 2020). "Indeed, 34a in colorectal cancer patients the expression of Smad4 and miRNA-34a show a significant inverse correlation and the overexpression of miRNA-34a inhibits autophagy activation by directly targeting Smad4 through the TGF-β/Smad4 pathway." (PMID 32792960, 2020). "Our results revealed that DUSP4 and Smad4 could regulate EMT of colorectal cancer through E-caderin, N-caderin, Vitmentin, and MMP9 gene." (PMID 32897241, 2020). "DUSP4 could aggravate cell proliferation, invasion, and migration in colorectal cancer by regulating Smad4 ubiquitylation degradation." (PMID 32897241, 2020). "To verify this hypothesis, SMAD4 overexpression plasmid was transfected into colorectal cancer cells and we examined the effects on cancer cell biological functions." (PMID 30979374, 2019). "Moreover, miR-34a mediates the resistance of oxaliplatin in colorectal cancer cells by inhibiting macroautophagy via the TGF-β/Smad4 pathway." (PMID 31349837, 2019). "An additional two had no associated tumor but a family history of such tumors in a first-degree relative (colorectal cancer at age 56 years for the individual with a SMAD4 translocation and renal cell carcinoma at age 69 for the individual with the TSC1 duplication)." (PMID 29909963, 2018). "Smad4 is a key component of TGFβ-Smad signaling and an important marker in colorectal cancer (CRC)." (PMID 29951173, 2018). "However, the single or combined overexpression of SUMO and Ubc9, together with that of wild type Smad4 were found to promote Smad4-dependent TGFβ-induced transcription in the human breast and colorectal carcinomas." (PMID 30096838, 2018). "Although we chose widely recognized pathological biomarkers in colorectal cancer, our data did not cover all molecular pathological markers that have been reported in the literature, such as the mutation status of SMAD4 and PTEN." (PMID 28623901, 2017). "It has been reported that Smad4 is a direct target of miR-454 in colorectal cancer." (PMID 27588500, 2016).